MSH6 (mutS homolog 6)
Diseases named in the same sentence as MSH6 in open-access papers (continued):
Sharing a sentence is not in itself a finding about the gene and the disease.
tumor (continued). "This same tumor also had six variants of uncertain significance: ARID2 c.1672C > T p.(R558C), FLT3 c.2546G > A p.(R849H), IGF1R c.3897C > G p.(N1298K), MSH6 c.1157C > G p.(P386R), PBRM1 c.2504G > A p.(R850H), and RNF43 c.1114C > T p.(P372S)." (PMID 31046843, 2019). "Validated variants showed that the tumor suppressor genes APC and ARID1 and the DNA MMR genes MSH3 and MSH6 are the genes with the highest numbers of validated variants." (PMID 31080553, 2019). "The detection of two nonsense MSH6 variants, a pathogenic POLE variant in tumor, and a mutational signature unique for MMR first\POLE second deficiency raised the concern for CMMRD." (PMID 31604779, 2019). "The MSH6 knockout, for example, bears striking similarity to those in MMR-deficient tumours—characterised by C>T and T<C substitution signatures and high burden of indels at polynucleotide repeat tracts." (PMID 29717121, 2018). "The tumor carried a KRAS mutation, and MLH-1, MSH-2, MSH-6, and PMS-2 immunostaining results were normal, suggesting microsatellite stability." (PMID 30043132, 2018). "To test for loss of protein product, we stained MLH1, MSH6, and PMS2 in tumour tissue from paraffin blocks, collected from the carriers of the coding variants." (PMID 30324682, 2018). "We found that restoration of MSH6 protein expression rescued tumor cell growth and therefore demonstrated that CSE1L effect on cell proliferation was largely dependent on MSH6." (PMID 28387323, 2017). "The results revealed that both tumor volume and weight were reduced in the MSH6 knockdown group than in the scramble control group." (PMID 28387323, 2017). "VUS T1219I has been described in a CRC patient who had a family history of CRC and a MSI tumor that stained positive for MSH6, the latter being consistent with the high levels of this variant protein we observed in mESCs." (PMID 28531214, 2017). "For the MSH6 promoter region, one tumor-derived DNA sample showed a consistently higher methylation level across 11 probes, located within a CGI and its north shore, when compared to the remaining 42 (Δβ ~8.37%)." (PMID 27902704, 2016).
tumor (continued). "Four relapsed tumours were hypermutable with 156–740 coding mutations, two of which had loss-of-function mutations in the DNA mismatch repair genes PMS2 and MSH6 at relapse." (PMID 25790293, 2015). "Interestingly, we found that two unrelated patients with these apparent discordances had the same mutation at MSH6 (c.1367GA; p.Trp456*), suggesting that in some circumstances the nature of the second hit could be determinant for the tumor’s IHC and MSI characteristics." (PMID 24244552, 2013). "Patients harboring mutations in the MSH6 gene present a lower risk of CRC and a more advanced age at first tumor diagnosis." (PMID 22547953, 2011). "Of the 23 MSH6-defective tumour samples of Dutch origin, matching normal DNA was available for 15 cases." (PMID 21081928, 2010). "Here, we used the pentaplex panel to evaluate MSI status in 29 tumours known to harbour an MSH6 defect." (PMID 21081928, 2010). "This tumour shows instability only in mononucleotide repeats, that is consistent with the higher incidence of MSI in this kind of markers in MSH6-deficient tumours described in the literature." (PMID 16940983, 2006). "Enlarging the standard (Bethesda) marker set with a mononucleotide marker (like BAT40) will increase the sensitivity of MSI analysis by minimising the chance of missing tumours with MSH6 inactivation." (PMID 17117178, 2006). "Both tumours stained negatively or very weakly for MSH6 protein, which is compatible with MMR deficiency associated with MSH6 mutation." (PMID 15354210, 2004).
tumor (continued). "It has also been shown to induce microsatellite instability through suppression of MSH6, facilitate liver metastasis via the miR-5692a/IL-8 axis, and modulate the tumor microenvironment through the outer membrane vesicles (OMVs) that induce immunosuppressive M2 macrophage polarization." (PMID 40944094, 2025). "The child had a family history of cancer, and subsequent investigation revealed a biallelic germline variant on MSH6 (c.3556+1G>A) with the absence of protein expression in both normal and tumor tissue." (PMID 40880425, 2025). "Pathogenic germline nonsense mutations in PMS2 (rs63750451) and MSH6 (rs267608094) were found in 2 patients, however, there was no indication of dMMR in the patients’ tumours, as the tumour mutation burden in these samples was < 1 mutation/Mb." (PMID 40389436, 2025). "One tumour possessed a KIAA1549::BRAF fusion alongside VEGFR2, MSH6, and LRP1B variants." (PMID 39948623, 2025). "In addition, variants in MMR pathway genes, MSH3, MSH6, LIG1, MCM9, and POLD3, were associated with relatively high MSI score and/or high mutational burden in 6 tumor samples." (PMID 41353477, 2025). "We report a case in which a patient with rapidly progressive metastatic castrate-resistant prostate cancer (mCRPC) was found to have an MSH6 mutation with microsatellite instability (MSI) and notably high tumor mutational burden (TMB) 109 mut/Mb, who had a complete response to pembrolizumab." (PMID 38920278, 2024). "IHC showed MSH6 expression in the tumour cells but with an irregular pattern." (PMID 38789506, 2024). "Immunohistochemistry (IHC) showed loss of MSH6 expression in tumour and non-neoplastic cells but was considered technically unreliable." (PMID 38789506, 2024). "In addition, normal immune cell populations express MSH6, necessitating strict separation of tumor cells from MSH6-positive immune cells." (PMID 38956208, 2024). "Among the 5 patients with a biallelic germline MSH6 mutation, 4 patients had a loss of expression of the MSH6 protein in the tumor and in non-neoplastic cells." (PMID 39233831, 2024). "We hypothesized that by using a higher threshold, we could account for positive internal controls (non-tumour cells expressing PMS2 or MSH6) that were erroneously classified as true positives." (PMID 39040241, 2024). "To exclude the impact of MSH6 mutations on our results, we downloaded the single nucleotide polymorphism data of UCEC from TCGA and obtained 432 MSH6 wild-type tumor samples and 75 MSH6 mutant tumor samples." (PMID 38390329, 2024). "However, tumours with germline MSH6 defects were only detected efficiently with IHC; seven out of eight LS tumours classified as MSS by either MSI assay had isolated MSH6 loss, compared to four out of twelve classified as MSI-H by both (p = 0.028)." (PMID 39682157, 2024).
tumor (continued). "Together, these data support the hypothesis that MMR homopolymer frameshifts act as a stochastic ON/OFF switch, dynamically regulating MSH6 expression during MMRd tumor evolution, akin to bacterial contingency loci." (PMID 38956208, 2024). "Stratifying regions by MSH6 labeling revealed a clear increase in infiltrating CD8-positive cytotoxic T cells, CD20-positive B cells, CD4-positive T cells and FoxP3-positive Treg cells in MSH6-deficient tumor regions." (PMID 38956208, 2024). "High MSH6 also yields prognostic value across other cancer types, suggesting that MSH6 may function to promote aggressive tumour behaviour." (PMID 36482191, 2023). "In this paper, the relationships between MSH6 levels in four biological fluids—whole blood, saliva, urine, and tissues—and tumor locations among the colorectal area, gross features, presence of a mucinous compound, molecular subtype, stroma features, and vascular invasions are presented." (PMID 38137434, 2023). "The ability to detect dMMR cases may lead to misdiagnosis by MSI testing alone, specifically MSH6 variations that tend to result in MSI-L or MSS in the tumor, which are more common in EC than CRC." (PMID 37663290, 2023). "Technical reasons might include the known weak staining of tumor nuclei by MSH6 and the subclonal nature of the IHC MSH6 findings." (PMID 36230473, 2022). "Furthermore, the promoting function of exosomal CTCF-mediated IGF2-AS through the miR-579-3p/MSH6 axis in OS cell resistance to CDDP was confirmed in tumor-bearing nude mice." (PMID 35693981, 2022).
tumor (continued). "The patient’s tumor showed loss of MLH1/PMS2 expression and isolated loss of MSH6 expression." (PMID 36077770, 2022). "Moreover, using the same algorithm, neoantigens predicted from somatic mutations of the genes MSH6, PIGO and AXIN2 observed in the LS-CRC tumour of one of the affected family members, was shown to induce interferon gamma (IFNγ) releasing T cell responses." (PMID 34067951, 2021). "Of note, we did identify one MSH6 germline PV amongst our EIN tumours with “borderline carcinoma” (n = 9), which could add evidence in support of inclusion of EIN in universal screening protocols in the future." (PMID 33467402, 2021). "Eight tumors exhibited solitary MSH6 loss, while isolated PMS2 loss was observed in only one tumor." (PMID 33816285, 2021). "In addition, the “Pathological Stage Plot” module of GEPIA2 was also used to analyze the relationship between MSH6 expression levels and different tumor pathological stages." (PMID 34941572, 2021). "Conventionally, the complete absence of MSH6 nuclear staining in both tumor and normal cells of the colonic mucosa is typically observed in patients with bi-allelic MSH6 mutation." (PMID 33422121, 2021). "MSH6 I927M is predicted to be uncertain significance as also supported by the finding that the respective TC sample did not exhibit a high TMB as would be expected in a microsatellite instable tumor." (PMID 34568003, 2021). "One available tumour specimen showed heterogeneous MSH6 status in immunohistochemistry." (PMID 33574476, 2021). "The immunohistochemical analysis of tumour samples showed increased yH2AX and ATM expression was associated with response, as well as increased expression of the mismatch repair proteins MLH1 & MSH6." (PMID 34256782, 2021). "However, currently, no pan-cancer analysis has been performed to comprehensively evaluate the relationship between MSH6 expression and the carcinogenesis and clinical prognosis of a variety of tumor types." (PMID 34941572, 2021). "Targeted sequencing of two tumor specimens used in MMR-IHC and plasma-derived circulating tumor DNA consistently revealed the detection of bi-allelic germline MSH6 c.3226C > T (p.R1076C) mutation, TMB-H as well as the genetic heterogeneity of the tumor samples." (PMID 33422121, 2021). "Moreover, several studies have demonstrated that MSH6 (an important component of the mismatch repair system) is a tumour-related factor that can affect tumorigenesis, proliferation, migration, and invasion effects." (PMID 34440667, 2021). "This could be because the proliferative and invasive behaviors of PIT1-lineage PAs might involve two factors: tumor proliferation promotion due to decreased MSH6/2 expression, and tumor immunity tolerance due to relatively high PD-L1 expression." (PMID 32325698, 2020).